TMEM35B (transmembrane protein 35B)
Synonyms: ZMYM6NB
Tractability: Antibody: UniProt predicts a signal peptide or a membrane-spanning region. PROTAC: ubiquitination databases record sites on it.
Gene: Protein-coding gene on chromosome 1 (34,981,380 to 34,985,347, reverse strand). Ensembl gene ENSG00000243749.
Subcellular location: Membrane
Subcellular location (Human Protein Atlas): Nucleoli; Nucleoplasm
Gene Ontology:
Cellular component: membrane
Genetic constraint (gnomAD): Loss-of-function variants: 7 observed, 8.51 expected, observed/expected ratio (o/e) 0.82, 90% interval 0.47 to 1.52. That is too few expected variants to judge how well the gene tolerates losing a copy. Missense variants: 176 observed, 181.75 expected, observed/expected ratio (o/e) 0.97, 90% interval 0.86 to 1.1. Synonymous variants: 89 observed, 83.72 expected, observed/expected ratio (o/e) 1.06, 90% interval 0.89 to 1.27.
Homologues: Orthologues: chimpanzee TMEM35B (100% identical), macaque TMEM35B (98% identical), guinea pig TMEM35B (68% identical), pig TMEM35B (68% identical), rabbit TMEM35B (67% identical), mouse Tmem35b (66% identical), rat Tmem35b (65% identical), tropical clawed frog tmem35b (51% identical), Drosophila melanogaster CG13920 (27% identical). Paralogues in human: TMEM35A (23% identical).